DEFB135 (defensin beta 135)
Description:
Has antibacterial activity.
Tractability: Antibody: UniProt places it where antibodies can reach, with high confidence; UniProt predicts a signal peptide or a membrane-spanning region; its Gene Ontology location is reachable by antibodies, with medium confidence.
Gene: Protein-coding gene on chromosome 8 (11,982,256 to 11,984,590, forward strand). Ensembl gene ENSG00000205883.
Subcellular location: Secreted
Pathways (Reactome):
Immune System: Beta defensins; Defensins
Gene Ontology:
Molecular function: membrane destabilizing activity
Biological process: innate immune response; killing of cells of another organism; defense response to Gram-negative bacterium
Cellular component: extracellular region
Genetic constraint (gnomAD): Loss-of-function variants: 14 observed, 8.24 expected, observed/expected ratio (o/e) 1.7, 90% interval 1.06 to 1.95. That is too few expected variants to judge how well the gene tolerates losing a copy. Missense variants: 135 observed, 87.98 expected, observed/expected ratio (o/e) 1.53, 90% interval 1.33 to 1.77. Synonymous variants: 51 observed, 31.82 expected, observed/expected ratio (o/e) 1.6, 90% interval 1.27 to 1.92.
Homologues: Orthologues: chimpanzee DEFB135 (99% identical), macaque DEFB135 (84% identical), dog DEFB135 (56% identical), mouse Defb30 (47% identical), rat Defb30 (45% identical). Paralogues in human: DEFB121 (36% identical), DEFB123 (32% identical), DEFB124 (31% identical), DEFB128 (29% identical), DEFB115 (26% identical), DEFB118 (26% identical), DEFB108C (25% identical), DEFB127 (25% identical), DEFB131A (25% identical), DEFB132 (25% identical), DEFB108B (23% identical), DEFB125 (23% identical), and 7 more.